STAT3 (signal transducer and activator of transcription 3)
Diseases named in the same sentence as STAT3 in open-access papers (continued):
Sharing a sentence is not in itself a finding about the gene and the disease.
tumor (continued). "The mean tumor volume in the Adv-Stat3(-) and MSC/Adv-Stat3(-) groups at day 52 was 248.3 ± 34.2 mm3 and 116.5 ± 20.1 mm3, respectively (P < 0.05)." (PMID 22054049, 2011). "Thus far, no role for Necdin in oncogenesis has been confirmed; however, our results suggest that repression of Necdin expression by STAT3 may be one mechanism which could potentially contribute to a growth advantage of tumor cells and is of interest for further analysis." (PMID 22046235, 2011). "We have shown in previous work that STAT3 dysregulation is frequently found in canine and human OSA cell lines and canine patient tumor samples." (PMID 21481226, 2011). "Recently, Niu and colleagues suggested that constitutively activated STAT3 up-regulated VEGF and induced tumor angiogenesis." (PMID 21731766, 2011). "IL-17 mediates signaling through distinct pathways in numerous inflammatory cells and tumor cells, such as MAPK, NF-κB, and STAT3 pathways." (PMID 22171994, 2011). "Finally, we examined whether Adv-Stat3(-)-loaded MSCs improve the survival of tumor-bearing mice." (PMID 22054049, 2011). "Second, in co-culture experiemtns with monocytes and tumor cells, monocytes enhance HCC cell proliferation, which was dependent on IL-6/STAT3 signaling pathway." (PMID 22136659, 2011). "Given that OSM is present in all canine patient tumor samples, it is plausible to infer that OSM in the tumor microenvironment in vivo likely enhances OSA basal Src and STAT3 activation and JAK2 phosphorylation." (PMID 21481226, 2011). "For instance, immunomodulators that have the capacity to induce IL-12 and IFN-γ with novel SMAD3/4 or STAT3 and STAT6 inhibitory molecules are potential targeted mixtures of polarizing the beneficial immune cells within tumor microenvironment." (PMID 21943203, 2011). "Although OSM has various and at times contradictory functions in many tumor types, in our cell lines OSM enhanced MMP2 and VEGF expression and function in part through STAT3 activation, thereby promoting tumor cell invasion." (PMID 21481226, 2011). "Tumor cells producing high levels of HGF can activate c-met by either autocrine or paracrine signaling mechanisms, which leads to Stat3 activation and gene transcription." (PMID 21595927, 2011). "In summary, the development of HCCs in DKO mice coincides with oxidative stress and the activation of tumor-promoting JNK1- and STAT3-signaling cascades." (PMID 21725989, 2011). "In contrast, Stattic, which prevents STAT3 dimerization by specifically interacting with its SH2 domain, is highly specific, and efficiently induces tumor cell death." (PMID 21486470, 2011). "In the present study, we found that E1A-mutant Adv-Stat3(-) at 500 MOI infection exponentially amplified in MSCs up to the utmost quantity in a sufficient time window, which consequently boosted the tumor apoptosis rate compared to direct virus treatment." (PMID 22054049, 2011). "The STAT3 inhibitor, NSC 74859, significantly suppressed tumor growth in vivo in mice with diethylinitrosamine (DEN)-induced HCC." (PMID 22136659, 2011). "The signal transducer and activator of transcription-3 (STAT3) induces transcription of genes that control differentiation, inflammation, proliferation, and tumor cell invasion." (PMID 21625522, 2011). "These indicated that STAT3 and AKT activation play an important role in the induction of proinvasive factors and hence tumor progression." (PMID 22171994, 2011). "Our data here indicate that JAK2 and STAT3 are activated by the cytokine OSM and that this cytokine is present in canine patient tumor samples." (PMID 21481226, 2011). "In this animal model, blockade of STAT3 with NSC 74859 induced tumor cell apoptosis, while inhibiting both tumor cells and monocytes proliferation." (PMID 22136659, 2011).
tumor (continued). "We had previously shown that STAT3 activation was present in a substantial number of OSA cell lines and primary canine OSA tumor samples and that inhibition of STAT3 using either a small molecule inhibitor or siRNA resulted in death of OSA cells in vitro." (PMID 21481226, 2011). "Recent studies have identified that STAT3 is a direct transcription activator of the VEGF gene and that activation of STAT3 leads to tumour angiogenesis." (PMID 20461084, 2010). "Recent studies have identified STAT3 as a direct transcription activator of the VEGF gene and showed that activation of STAT3 leads to tumour angiogenesis in vivo." (PMID 20461084, 2010). "In the study described here, we investigated the role of NF-κB, STAT3 and PI3K signaling in LBL, the most prevalent tumor type in the iMycEμ mice." (PMID 20433747, 2010). "To determine whether NF-κB and STAT3 activation occurred before tumors were present, we examined NF-κB and STAT3 activity in splenic B cells from tumor-free (premalignant) or tumor-bearing (malignant) iMycEμ mice, using splenomegaly and age as two independent indicators of tumor progression." (PMID 20433747, 2010). "Activated STAT1, STAT3 and STAT5 are often observed in solid and liquid tumors, and are required for tumor transformation and progression which involves a set of oncogenes such as EGFR, Ras, Src, and FAK." (PMID 20576130, 2010). "Inhibition of Stat3 activation blocks HIF-1 and VEGF expression in vitro and inhibits tumor growth and angiogenesis in vivo." (PMID 20204067, 2010). "The activation of STAT3 has also been shown to upregulate vascular endothelial growth factor (VEGF) expression and promote tumour angiogenesis." (PMID 20461084, 2010). "IL11 increased pSTAT3/STAT3 in all tumour cell lines, while SOCS3 abundance was increased only in one tumour cell line." (PMID 20553623, 2010). "The phosphorylated STAT-3 (p-STAT-3) then translocates into the nucleus and induces a variety of transcriptional factors that propagate tumorigenesis and up-regulate tumor-mediated immunosuppressive factors." (PMID 19900287, 2009). "Our data demonstrate that constitutive activation of STAT3 is present in both canine and human OSA cell lines and in a subset of canine OSA fresh tumor specimens." (PMID 19284568, 2009). "Tissue samples of primary tumours from patients suffering from SCLC (n=10) and NSCLC (n=13) were stained with anti-phospho-Tyr705 STAT3 and anti-STAT3 antibodies in immunohistochemistry." (PMID 19455144, 2009). "Based on recent reports suggesting the role of Stat3 in the expression of VEGF and tumor angiogenesis, we evaluated the levels of VEGF in the skin sections of mice treated with DMBA." (PMID 19440292, 2009). "STAT3 is known to regulate the transcription of MMP2, a matrix metalloproteinase known to be important in tumor cell migration and metastasis." (PMID 19284568, 2009). "In the present study we further set out to establish a possible role of GM3 expression and STAT3 activation in tumor immune escape and angiogenesis in NSCLC, since both are considered as novel therapeutic targets for this tumor type." (PMID 19519895, 2009). "However, since activated STAT3 may lead to several other carcinogenic mechanisms, such as resistance to apoptosis, angiogenesis, and tumor invasion, it is possible that paracrine activation of STAT3 in MDA-MB-453 cells may lead to those significant cancerous phenotypes." (PMID 18939993, 2008). "We recently observed that NCX-4016, an isomeric form of NCX-4040, inhibited tumor growth by modulating EGFR/PI3K and STAT3 signaling pathways." (PMID 18302761, 2008). "Recently, we have shown that NCX-4016 suppressed the growth of cisplatin-resistant human ovarian xenograft tumor (A2780 cDDP) in mice by inducing G1 cell-cycle arrest and apoptosis though inhibition of EGFR/PI3K and STAT3 signaling pathways." (PMID 18302761, 2008).
tumor (continued). "The novel microtubule destabilizing agent ENMD-1198 is suitable for inhibiting HIF-1α and STAT3 in human HCC cells and leads to reduced tumor growth and vascularization in vivo." (PMID 18651980, 2008). "To Target Stat3 signaling pathway using Stat3β upregulates TRAIL and a secretory apoptotic signal(s) in B16 tumor cells." (PMID 18939995, 2008). "NCX-4040, in combination with cisplatin, inhibited tumor growth by downregulation of EGFR and STAT3 signaling." (PMID 18302761, 2008). "After approximately 30 days, the tumor volume in PBS control group increased to 639 ± 43 mm3, whereas the tumor volume in STAT3 decoy ODN treatment group was only 195 ± 24 mm3, indicating that the tumor growth was inhibited by 69.5% (p < 0.01)." (PMID 17683579, 2007). "Despite considerable heterogeneity in activated STAT3 IHC staining as displayed from the images, an increase in staining is noticeable after EGF stimulation within the viable tumor area which is in agreement with Western blotting." (PMID 17326824, 2007). "Therefore, STAT3 may be a promising target for treatment of tumor cells." (PMID 17683579, 2007). "In sum, the model which emerges is one in which STAT3 signalling downstream from EGFR is required for persistent cell motility and invasion, and that partial abrogation of this pathway hinders this tumour progression." (PMID 16804520, 2006). "Preliminary data on microarray and immunoblot demonstrate a potential relationship between EGFR/STAT3 signalling pathway and the expression of ena/VASP and caspase 3, which related to cell motility and apoptosis, both key processes in tumour progression." (PMID 16804520, 2006). "Constitutively activated signal transducers and activators of transcription (STAT) factors, in particular STAT1, STAT3 and STAT5, have been demonstrated in a variety of human tumours and cancer cell lines." (PMID 12865928, 2003). "The results showed that constitutive activation of STAT3 and STAT5 was detected in the majority, 70.5 and 62.3%, respectively, of the 61 tumour specimens." (PMID 12865928, 2003). "Mechanistically, RNA-based therapeutics MALAT1 activates the EZH2/STAT3 axis, modulates the HIF-1α-KDM3A pathway under hypoxia, interacts with FAM46C to drive migration, and sponges tumor-suppressive miRNAs such as miR-125b, miR-1271-5p, miR-509-5p, miR-188-5p, and miR-15a/16." (PMID 41596492, 2026). "Importantly, the STAT3/SLC1A4 axis regulated cysteine uptake, tumor killing by T cells and the efficacy of anti-PD-L1 immunotherapy." (PMID 41604939, 2026). "The acetylated STAT3 upregulates the expression of ACSL4, which leads to increased phospholipid synthesis and enhances mitochondrial integrity, thus overcoming chemotherapy-induced tumor cell apoptosis (Lower left)." (PMID 41513612, 2026). "In line, overexpression of wildtype Tm4sf1 in Zdhhc20 silenced 4T1 tumor spheroids failed to rescue STAT3 phosphorylation, KAT2A gene and protein expression in the presence and absence of extra palmitate." (PMID 41826695, 2026). "A single intravenous administration of SD-965 effectively induces rapid, complete, and durable depletion of STAT3 protein in mouse native and human xenograft tumor tissues with no depletion of other STAT proteins." (PMID 41871272, 2026). "In detail, STAT3, activated by cytokines such as IL‐6 and IL‐10 alongside growth factors including epidermal and fibroblast, mediates JAK/STAT signaling, a pathway critical for tumor progression and chemoresistance." (PMID 41509196, 2026). "Microbial superantigens and exotoxins may further contribute to tumor progression and therapeutic resistance by reinforcing JAK/STAT signaling, particularly STAT3, and reducing CD8+ T-cell-mediated immune surveillance." (PMID 41976391, 2026). "However, paracrine signalling mediates their role in HCC cell proliferation, migration, invasion, as well as enhancing tumour growth, as they activate pathways, including NF-κB, ERK, IL-6/STAT3 and Wnt/β-catenin." (PMID 41476776, 2026).
tumor (continued). "Moreover, treatment with these inhibitors disrupts CRC cell adaptation to acidic stress by interfering with tumor acidity regulation, suggesting a novel acid-modulating role for anticancer drugs that target integrin, FAK, and STAT3." (PMID 41535258, 2026). "Knocking down OSMR dramatically reduces tumor cell proliferation, invasion, and migration, accelerates cell death and cell cycle arrest, and lowers JAK and STAT3 phosphorylation as well as CCL-2 expression levels, all while decreasing the fraction of M2 macrophages." (PMID 40161370, 2025). "Importantly, inhibition of STAT3 (with SH4-54) and VEGF-A (with bevacizumab) partially reversed LCN2-driven tumor growth in BM-bearing mice." (PMID 41436606, 2025). "The mechanism underlying CD8+ T cell exhaustion induced by IL-6 may involve the activation of the STAT3 pathway via NF-κB and IL-6-GP130-Janus kinase (JAK) signaling pathways, thereby exerting inhibitory effects on tumor progression." (PMID 41200178, 2025). "Furthermore, activation of the STAT3 pathway leads to increased secretion of vascular endothelial growth factor A (VEGFA), enhancing angiogenesis and further facilitating tumor metastasis." (PMID 40474298, 2025). "A dysfunctional STAT1 variant, which is unable to translocate into the nucleus upon cytokine stimulation and fails to inhibit STAT3, can trigger lymphomagenesis, as STAT3 becomes more active and contributes to lymphoid malignancy and tumor progression." (PMID 40287766, 2025). "Furthermore, tumor-derived exosomal heat shock protein 72 enhances MDSC expansion by activating STAT3 via TLR2/MyD88-dependent autocrine IL-6 production, reinforcing an immunosuppressive tumor microenvironment TME." (PMID 40861469, 2025). "Across diverse tumor models, IVM demonstrates consistent antitumor activity through the induction of apoptosis, oxidative stress, mitochondrial dysfunction, and inhibition of key signaling pathways, including NF-κB, mTOR/STAT3, and importin β." (PMID 41155573, 2025). "We demonstrated that inhibition of tumor-macrophage symbiosis via blockade of integrin αv combined or not combined with GSK3β or STAT3 inhibition promotes the infiltration and activation of T cells, especially CD8+ T cells, in the GBM TME." (PMID 40131864, 2025). "Additionally, curcumin enhances anti-tumor immunity in APC by elevating CD8+ T cell function and downregulating the AKT/mTORC1/STAT3/PD-L1 axis." (PMID 40943396, 2025). "Overall, phenolic compounds induce apoptosis, inhibit metastasis, and modulate oxidative stress and oncogenic signaling pathways whereas flavonoids regulate cell cycle progression, trigger ROS-mediated apoptosis, and suppress tumor proliferation via MAPK, PI3K/Akt, and STAT3 inhibition." (PMID 41517157, 2025). "The activation of pro-inflammatory signaling pathways, such as nuclear factor-kappa B (NF-κB) and signal transducer and activator of transcription 3 (STAT3), in the tumor microenvironment promotes cancer cell proliferation, survival, angiogenesis, and metastasis." (PMID 40040878, 2025). "Additional approaches seek to destabilize the suppressive Treg lineage by targeting transcriptional and metabolic pathways, including STAT3 inhibition, COX-2/PGE2 blockade, and disruption of the PD-1–SHP-2 axis, each of which can reduce Treg-mediated suppression in tumor tissues." (PMID 41426337, 2025). "In vitro, SIL@T NPs effectively inhibited STAT3 activation and induced ICD in tumor cells." (PMID 40733107, 2025). "Notably, traditional Chinese medicine YiFeiSanjieWan mitigates CRF symptoms by inhibiting the Stat3/HIF-1α/BNIP3 signaling pathway, which is induced by aberrantly activated tumor-related inflammation." (PMID 41018226, 2025). "STAT3 is frequently aberrantly hyperactivated in both cancerous and non-cancerous cells within the tumor microenvironment, driving the production of immunosuppressive factors, promoting uncontrolled cancer cell proliferation, and inhibiting apoptosis." (PMID 40943567, 2025).
tumor (continued). "Furthermore, IL-6-mediated STAT3 activation induces the expression of S100A9, a factor that promotes tumor invasion and metastasis." (PMID 41409248, 2025). "Since JAK–STAT3 activation promotes macrophage recruitment, M2 polarization, and immunosuppression during tumor progression, we hypothesized that ITGA2hi‐PTC regulates M2 polarization via JAK2/STAT3 signaling." (PMID 40985182, 2025). "To investigate the clinical relevance of the B7‐H3/c‐Met/STAT3 signaling axis in patient survival, we first retrieved both CRC and GBM patient data from the TCGA dataset since both CRC and GBM tumor cell lines have been examined in the in vitro biochemical studies in this report." (PMID 40859957, 2025). "In contrast, the expression levels of STAT3 downstream target genes—such as VEGFA, IL-6, MMP13, Bcl2, and Twist1—remained comparable across all experimental groups, likely due to tumor excision occurring at a stage when metastasis was already underway." (PMID 40806360, 2025). "Enhanced STAT3 activation in TANs leads to significantly reduced secretion of myeloperoxidase, neutrophil elastase, and TRAIL, while concurrently inducing markedly elevated expression of MMP9 and Bv8 genes, which favors tumor angiogenesis and growth." (PMID 41254689, 2025). "Research shows that they can interfere with multiple signaling pathways in cancer cells, like NF-κB and STAT3 (which promote inflammation and cell survival), PI3K/Akt (involved in cell growth), and processes that lead to tumor invasion (like the epithelial–mesenchymal transition)." (PMID 40427617, 2025). "Consistently, the absence of STAT3 in SNAIL-driven SCC tumors results in diminished tumor size and growth." (PMID 40399946, 2025). "These pathways, including the STAT3, RAS-MAPK, and PI3K pathways, result in the inactivation of proteins that trigger apoptosis and the upregulation of genes that promote cell growth, thereby facilitating tumor cell proliferation." (PMID 39780275, 2025). "Aging causes an accumulation of senescent cells that secrete a range of cytokines, growth factors, and enzymes (SASPs), which remodel the ECM, making it stiffer and more degradable, and activate pro-metastatic pathways like TGF-β, STAT3, and MAPK, aiding processes like EMT and tumor invasion." (PMID 41373662, 2025). "Additionally, STAT3 inhibition in dendritic cells has been shown to suppress STAT5 signaling, impairing T cell priming and diminishing anti-tumor immune responses." (PMID 41287778, 2025). "Mechanistically, CPA4 activates the STAT3 and ERK pathways, contributing to tumor progression." (PMID 40805261, 2025). "Previous research has revealed that OSMR’s participation in cancer is strongly tied to the JAK/STAT3 signaling pathway, and that inhibiting the STAT3/CCL2 signaling pathway may inhibit tumor malignancy." (PMID 40161370, 2025). "The tumor progression, including resistance of apoptosis, angiogenesis, and proliferation, is strongly influenced by higher infiltration of M2‐TAM (CD163 and 204) and upregulation of STAT3, NF‐κB pathways." (PMID 41263059, 2025). "Moreover, the expression of putative Stat3 target genes Abca3 and Etv5 significantly decreased in Stattic-treated KPY tumor organoid cells compared to DMSO treatment (Fig. EV2I)." (PMID 39930268, 2025). "Through activating the STAT3 signaling pathway, IL6 promotes critical processes such as angiogenesis, epithelial-to-mesenchymal transition (EMT), and immune evasion, all contributing to tumor progression and therapeutic resistance." (PMID 40427188, 2025). "Additionally, dioscin elicits anti-tumor immunity by inhibiting M2 macrophage polarization through the JNK and STAT3 pathways in lung cancer." (PMID 40302816, 2025).